HMGB1 (high mobility group box 1)
Diseases named in the same sentence as HMGB1 in open-access papers (continued):
Sharing a sentence is not in itself a finding about the gene and the disease.
Parkinson disease (continued). "Besides the small molecules, anti-HMGB1 monoclonal antibody (mAb) had been demonstrated to neutralize the released HMGB1, prevent the inflammation cascade, and afford a therapeutic effect in ischemic brain injury, traumatic brain injury, Parkinson’s disease, and SCI." (PMID 33036632, 2020). "Recently, it was reported that chronic neuroinflammation may be a driving force of progressive neurodegeneration and that HMGB1 provides the link between chronic neuroinflammation and progressive neurodegeneration in neurodegenerative diseases, such as Parkinson's disease." (PMID 24733965, 2014). "The weight of evidence indicates that the engagement of high-mobility group protein B1 (HMGB1) and alpha synuclein plays a major part in exacerbating the pathology of Parkinson’s disease." (PMID 25856766, 2015). "Additionally, RA inhibited NF-κB nuclear expressions and downregulated the HMGB1, Myd88, and TLR4 expressions in cell and animal models of Parkinson’s disease." (PMID 34827094, 2021).
liver diseases (41 papers, 2011 to 2026). "Previous studies have shown that serum HMGB1 level is positively associated with the severity of liver disease, readmission, and mortality." (PMID 36944948, 2023). "HMGB1 was originally discovered as a nuclear binding protein, and it has been implicated in various hepatic diseases." (PMID 35000581, 2022). "Aberrant extracellular release of high-mobility group box1 (HMGB1) is associated with many forms of liver disease." (PMID 34934826, 2021). "Because of this functional diversity, HMGB1 has been implicated in the pathogenesis of many common liver diseases and is being considered as a potential therapeutic target." (PMID 31731454, 2019). "As HMGB1 dysfunction has been implicated in various forms of liver disease, ranging from liver damage to fibrosis, as well as in tumorigenesis, our novel findings further elucidate the precise role of HMGB1 in HBV‐related diseases." (PMID 29316268, 2018). "Previous studies have strongly suggested a role for HMGB1 as a mediator of inflammation in hepatic disorders, and hepatocytes have been considered the main source of extracellular HMGB1 associated with the immune response during acute hepatic failure." (PMID 30258438, 2018). "HMGB1 dysfunction has been implicated in various forms of liver disease ranging from liver damage to fibrosis, as well as tumorigenesis." (PMID 25126737, 2014). "Large-scale studies assessing various tumor types or underlying liver diseases are necessary to determine whether HMGB1 alone or in combination with other parameters could serve as a valuable tool for preoperative risk assessment." (PMID 39000266, 2024). "HMGB1, an inflammatory mediator, secreted by damaged liver cells, prolongs the inflammatory response, playing a key role in diverse pathogenic mechanisms in liver disease, such as inflammation, fibrosis, steatosis and tumorigenesis." (PMID 36081910, 2022). "Accordingly, targeting of HMGB1 could potentially reduce the occurrence and pathogenesis of schistosome-induced liver disease, although the underlying mechanism remains unclear." (PMID 35335612, 2022). "HMGB1 contributes to the pathogenesis of multiple liver diseases, such as hepatic IRI and acute liver rejection, through TLRs." (PMID 38716542, 2024). "Further investigation is necessary to elucidate the specific functions of different HMGB1 subtypes in the liver and their potential contributions to various liver diseases." (PMID 39349828, 2024). "Liver disease progression was associated with lower nadir CD4+ T-cell count and higher levels of HMGB1 at baseline." (PMID 38518655, 2024). "HMGB1 has been identified previously as an important marker and mediator of liver disease pathogenesis in HBV mono-infection, with a range of roles demonstrated in vitro and murine studies including stellate cell activation and fibrogenesis." (PMID 38518655, 2024). "HMGB1 acts as a pro-inflammatory cytokine that contributes to liver damage in a variety of liver diseases, including alcoholic liver disease." (PMID 37298365, 2023). "Other studies reported that the suppression of HMGB1 using agents like glycyrrhizic acid and salvianolic acid B offered therapeutic benefits in the treatment of cardiac fibrosis and liver disease, respectively, in rat models." (PMID 38139865, 2023). "Another important aspect related to HMGB1 and compulsive alcohol consumption is alcoholism-related liver disease." (PMID 37298365, 2023). "Regardless, the discoveries discussed in this review describe the current knowledge of the roles of HMGB1 in liver disease, with an emphasis on schistosomiasis." (PMID 35335612, 2022). "Given that the lives of hundreds of millions of people are threatened by schistosomiasis, further research efforts should focus on HMGB1 as a potential therapeutic target for schistosome-induced liver disease." (PMID 35335612, 2022). "To date, limited studies have investigated the relationship between HMGB1 and schistosome-induced liver disease." (PMID 35335612, 2022).
liver diseases (continued). "Numerous studies have also suggested HMGB1 as a therapeutic target for liver diseases by blocking the release of HMGB1 or inhibiting the activity of extracellular HMGB1." (PMID 35335612, 2022). "From our previous studies, we established the significance of the protein-coding function of HMGB1 in liver diseases including NAFLD and HCC12–15." (PMID 34916485, 2021). "Glycyrrhizin (GL), a traditional Chinese medicine for liver disease, binds to HMGB1, thereby inhibits tissue injury." (PMID 34934826, 2021). "Recently, HMGB1 has been identified as a potent inflammatory mediator in several liver diseases, and mounting evidence indicates an important role of extracellular HMGB1 in the development of NAFLD." (PMID 33238880, 2020). "It has been used in preclinical investigations to inhibit HMGB1 signaling to treat inflammation in lung and liver diseases." (PMID 31560698, 2019). "Nevertheless, further basic and clinical studies on various HMGB1 isoforms and HMGB1 protein complexes in the context of liver diseases are warranted to identity means to exploit this therapeutically." (PMID 31731454, 2019). "HMGB1 is predominantly secreted by inflammatory cells and potentially plays a role in regulating the pathophysiology of liver diseases." (PMID 31417535, 2019). "Glycyrrhizin, a phytochemical that directly inhibits HMGB1, is widely used for the treatment of liver disease in Asia, and there are indications that glycyrrhizin can reduce HCC development in certain patient subsets." (PMID 31731454, 2019). "HMGB1 is also well known to play a key role in sterile (i.e., non-microbial) inflammation, a key process that occurs in common liver diseases such as non-alcoholic steatohepatitis, alcoholic steatohepatitis, and drug-induced liver injury (DILI)." (PMID 31731454, 2019). "In this review, we will discuss the critical role of HMGB1 in these pathogenic contexts and propose HMGB1 as a bona fide and targetable DAMP in the setting of common liver diseases." (PMID 31731454, 2019). "Understanding the crosstalk between HBx and HMGB1 in more detail will provide better insight into HBx‐mediated biological functions and will guide therapeutic intervention in liver diseases." (PMID 29316268, 2018). "HMGB1 release has been observed in hepatocytes from patients suffering from various liver diseases, and the cytoplasmic translocation of HMGB1 has been observed in patients with acute liver failure." (PMID 25187820, 2014). "Extensive research is needed to determine the relationship between HMGB1, autophagy, and liver diseases." (PMID 25126737, 2014). "Therefore, regulating the release of HMGB1 and its signaling pathway is regarded as an important strategy for the treatment of liver disease." (PMID 40003959, 2025). "In addition, HMGB1 levels in these patients effectively predicted hospital readmission for liver disease as well as transplantation or death within 90 days." (PMID 37298365, 2023). "HMGB1, originally discovered as a nuclear binding protein, is involved in various hepatic diseases." (PMID 35000581, 2022). "In the present study, serum from HEV-induced hepatic diseases, and HMGB1 promoted apoptosis in HL-7702 cells, which may participate in disease pathogenesis of HEV-induced hepatic diseases, including AVH, ALF and ACLF." (PMID 35000581, 2022). "This article highlighted the emerging roles of HMGB1 in liver diseases." (PMID 35335612, 2022). "HMGB1 is released by injured liver cells, which may prolong inflammatory responses and promote the progression of liver disease." (PMID 36081910, 2022). "Our previous studies revealed HMGB1-driven signaling mechanisms in several types of liver diseases." (PMID 34916485, 2021). "In this study, we focused our efforts on understanding whether the liver disease-related gene, HMGB1, participated in epigenetic regulatory mechanisms beyond its potential as a protein-coding gene." (PMID 34916485, 2021).
liver diseases (continued). "Inflammasome triggers or amplify liver diseases by releasing pro-inflammatory cytokines such as IL-1β, IL-1α, IL-18, and also through other inflammatory mediators such as High Mobility Group Box 1 (HMGB1)." (PMID 32431709, 2020). "Studies in preclinical animal models using HMGB1 antagonists also clearly supports the notion that blocking excessive amounts of extracellular HMGB1 offers an attractive therapeutic target to ameliorate inflammatory liver diseases." (PMID 31731454, 2019). "Therefore, extensive research is still needed to determine the relationship between the viral protein HBx, the host protein HMGB1, and liver diseases." (PMID 29316268, 2018). "Considering the pivotal role of HBx and HMGB1 in the pathological process of liver diseases, we proposed that there might be a functional crosstalk between HBx and HMGB1." (PMID 29316268, 2018). "Increasing evidences have demonstrated HMGB1 act as a critical molecular target in multiple human diseases including infectious diseases, acute lung injury, brain injury, liver disease, intestinal barrier disruption, vascular barrier disruption, precancerous lesions." (PMID 28754974, 2017). "Additionally, HMGB1 influences mitochondrial oxidative phosphorylation, free fatty acid ß-oxidation, and immune cell recruitment and activation, highlighting its multifaceted involvement in liver disease progression." (PMID 39000266, 2024). "Thus, HMGB1 is a protumorigenic factor in the context of liver diseases." (PMID 31731454, 2019). "Since HMGB1 can aggravate the formation of NETs, targeting this crosstalk can offer a novel therapeutic target for the treatment of AILI and other liver diseases." (PMID 40003959, 2025). "However, it remains controversial whether HMGB1 is required for autophagy in liver diseases." (PMID 29316268, 2018). "High‐mobility group box 1 (HMGB1) is a member of the HMG family, which plays a pivotal role in various forms of liver disease related to liver damage, fibrosis, and tumorigenesis." (PMID 29316268, 2018). "HMGB1 and RAGE are also expressed in human liver cells including Hepg2 cells and related with liver disorders such as hepatic injury and liver ischemia." (PMID 26391982, 2015). "High-mobility group box-1 (HMGB1), a DNA-binding non-histone nuclear protein, is typically produced in eukaryotic cells and is one of the most researched DAMPs in liver disease." (PMID 37298621, 2023). "The same signals may play a similar role in different liver diseases; for example, HMGB1 released by hepatocytes triggers KC activation in AILI, I/R, and NASH, indicating similar functions of macrophages in various liver diseases." (PMID 32362892, 2020). "Additional studies have also reported that endogenous ligands for TREM1, HMGB1 and HSP70, are also upregulated in various liver diseases and may further drive hepatic inflammation through TREM1." (PMID 31260499, 2019). "We will next describe below the role of HMGB1 in the context of common liver diseases such as non-alcoholic fatty liver disease (NAFLD), alcoholic liver disease (ALD), and drug-induced liver injury (DILI)." (PMID 31731454, 2019). "Cytoplasmic HMGB1 translocation may occur during ALF, which may potentially contribute to the pathogenesis of liver inflammatory diseases." (PMID 21406085, 2011). "Collectively, these data highlight the complex relationship between inflammatory mediators and liver diseases, positioning GDF-15 and HMGB1 as central mediators of hepatic and systemic inflammation in PALF and further recasting MIG as a chemokine that may help control inflammation." (PMID 40809145, 2024). "For this purpose, various serum biomarkers have been proposed, such as alanine aminotransferase (ALT), sorbitol dehydrogenase (SDH), glutathione S-transferase (GSTα), GLDH, microRNAs, CK-18, and HMGB-1, but these are not specific of DILI or liver disease." (PMID 26824035, 2015).
brain injury (40 papers, 2014 to 2025). Acute and chronic (see also brain INJURIES, CHRONIC) injuries to the brain, including the cerebral hemispheres, CEREBELLUM, and brain STEM. "As an endogenous damage‐associated molecular pattern (DAMP), HMGB1 plays a crucial role in mediating inflammation and the innate immune response in various neurological diseases including neonatal HI brain injury." (PMID 39496476, 2024). "However, some work has implicated HMGB1 as a promotor of recovery following brain injury." (PMID 33731757, 2021). "Similar neuroprotective effects of anti-HMGB1 mAbs have been reported in rodent models of ischemic brain injury, intracranial hemorrhage, and traumatic brain injury, as well as in a mouse model of spinal cord injury." (PMID 40943562, 2025). "In our previous study, we showed that fluid percussion-induced brain trauma in rats leads to remarkable HMGB1 translocation and release, mainly from neurons in the affected areas, within 24–48 h after the injury." (PMID 38892076, 2024). "HMGB1 A-box significantly reduces brain edema, improves cellular degeneration, reduces the expression of pro-inflammatory cytokines in post-traumatic brain injury, and improves behavioral performance in TBI mice by protecting the integrity of the BBB." (PMID 36388178, 2022). "The extracellular release of HMGB1 is induced when cells are stimulated, and HMGB1 is considered an important new target for treating various inflammatory diseases, including brain injury and cancer." (PMID 34366853, 2021). "High mobility group box-1, as a late inflammatory factor and immunoregulatory molecule, has been reported to be elevated during the acute and subacute phases (3–12 h) of brain injury and to gradually return to normal levels up to 4 weeks post injury." (PMID 34539383, 2021). "High mobility group box-1 (HMGB1), a ubiquitous nuclear protein, is one of the many danger signals released by immune cells or necrotic cells after brain injuries." (PMID 34830412, 2021). "It was reported that the plasma and CSF levels of HMGB1 increased significantly in patients with brain trauma and that the elevated levels predicted the outcome of patients." (PMID 33321691, 2020). "Using this anti-HMGB1 mAb, we have previously demonstrated its beneficial effects on different types of inflammatory disease, such as ischemic and traumatic brain injury." (PMID 26067826, 2015). "Taken together, we speculated that HMGB1 release may act as an upstream event in a cascade leading to a diverse range of brain injuries." (PMID 38892076, 2024). "Interestingly, down-regulation of the high-mobility group box 1 (HMGB1)/TLR4 pathway is believed to be responsible for functional recovery in rodents with brain injury following MSCs-derived exosome transplantation." (PMID 35986375, 2022). "Such a paradigm could be incorporated into experiments exposing OPCs to disulfide HMGB1 to further assessment of how this DAMP may influence remyelination following models of brain trauma." (PMID 33731757, 2021). "In vivo, ischemic brain injury leads to a decrease of HMGB1 immunoreactive cells in the ischemic cortex and an increase of HMGB1 in serum, which could be attenuated by moderate cooling during ischemia." (PMID 34776788, 2021). "Moreover, we have also recently shown that HMGB1 and IAIPs bind to each other in vitro and are co-localized both in the nucleus and cytoplasm after HI-related brain injury." (PMID 34639091, 2021). "The results of this study suggest that ω-3 PUFA supplementation attenuates the inflammatory response by modulating microglial polarization through SIRT1-mediated deacetylation of the HMGB1/NF-κB pathway, leading to neuroprotective effects following experimental traumatic brain injury." (PMID 29678169, 2018). "Moreover, the inhibition of HMGB1 mobilization by anti-HMGB1 was common to different types of brain injuries, suggesting the existence of HMGB1-induced mechanisms of HMGB1 release in all brain injuries examined." (PMID 28446773, 2017).